NOS2 (nitric oxide synthase 2)
Diseases named in the same sentence as NOS2 in open-access papers (continued):
Sharing a sentence is not in itself a finding about the gene and the disease.
psoriasis (27 papers, 2012 to 2025). An autoimmune condition characterized by red, well-delineated plaques with silvery scales that are usually on the extensor surfaces and scalp. "Rs4795067 is a polymorphism located in an intron of the nitric oxide synthase 2 (NOS2) gene, which is associated with psoriasis, with the risk allele G." (PMID 38898675, 2024). "We demonstrated that the psoriasis-associated miRNA, miR-31, was induced by IL-17 and prevented the full translation of the IL-17-induced NOS2 mRNA." (PMID 38926337, 2024). "These were attributed to disease-risk loci including loci in or near NOS2 (psoriasis), TLR1 (eczema and allergic disease phenotypes), and FADS2 (vitiligo)." (PMID 39137780, 2024). "Here, we investigate the functional significance of the susceptibility gene NOS2 in the pathogenesis of psoriasis and translate our findings into a novel therapeutic strategy." (PMID 38926337, 2024). "Here, we report that IL-17 induces the expression of the psoriasis susceptibility gene NOS2 in keratinocytes and that NOS2-derived NO mediates IL-17 downstream effects." (PMID 38926337, 2024). "Nitric oxide synthase 2 (NOS2) has been identified as a susceptibility gene in psoriasis, as well as in other inflammatory disorders." (PMID 38926337, 2024). "One SNP (rs2070721) in IRF1 and SNPs (rs2297518 and rs4795067) in NOS2 are also associated with autoimmune diseases, such as multiple sclerosis (MS) in Italy, AS in Europe, and psoriasis in Pakistan." (PMID 27965977, 2016). "However, NOS2 associations have been reported for various other conditions, including a GWAS association between rs4795067 and psoriasis." (PMID 36672920, 2023). "Moreover, it has been known that the locus containing the inducible nitric oxide synthase (NOS2) gene is associated with psoriasis susceptibility." (PMID 35321240, 2022). "Additionally, we found genome-wide significant association to the previously reported psoriasis risk loci; NOS2 (rs4795067, p=5.27×10−9)." (PMID 25923216, 2015). "We also confirm association of PsA with a previously reported psoriasis locus, NOS2, bringing the total number of confirmed, genome-wide significant, PsA loci to 10 including 4 that are PsA-specific (HLA-B, chromosome 5q31, PsA-specific variants within IL23R and now PTPN22)." (PMID 25923216, 2015). "As a result, both the NOS2 KO and NO donor cream experiments suggest that either eradicating or enhancing the cellular NO level reduces the psoriasis-like inflammation and proliferation in the skin." (PMID 38926337, 2024). "The target proteins of these active compounds, including IL1B, TNF, STAT3, IL6, NOS2, and NFKBIA, were found to be directly associated with psoriasis-related disease proteins." (PMID 39590306, 2024). "A functional role of NOS2 in psoriasis pathogenesis is further supported by its distinctively upregulated gene expression in psoriatic involved skin in contrast to low expression in different clinical types of eczema." (PMID 38926337, 2024). "Future studies should investigate disease‐specific biomarkers, such as NOS2 (psoriasis) and CCL27 (eczema) in different palmar skin diseases." (PMID 32333380, 2020). "NO synthase 2 (NOS2) that generates NO is found to be expressed in inflammatory skin barrier diseases such as psoriasis." (PMID 31752827, 2019). "Nevertheless, 7 of the PP-increased DEGs were associated with psoriasis susceptibility loci (LCE3D, IFIH1, GRHL3, IL12B, PRSS53, REL and NOS2), and 1 PP-decreased DEG was near a psoriasis susceptibility locus (SDC4)." (PMID 24260178, 2013). "These sub-groups correlated with the composition of the inflammatory infiltrate, but were only weakly associated with increased risk allele frequency at some psoriasis susceptibility loci (e.g., REL, TRAF3IP2 and NOS2)." (PMID 22479649, 2012). "Moreover, we identified an association between Streptococcus abundance and psoriasis severity in patients with genetic variants related to IL-22, ERAP1, NOS2, and ILF3." (PMID 38898675, 2024).
psoriasis (continued). "In conclusion, we demonstrate that IL-17 induces NOS2 and fine-tunes its translation towards a window of proinflammatory and hyperproliferative effects and identify NO donor therapy as a new treatment modality for psoriasis." (PMID 38926337, 2024). "Therefore, potential diagnostic biomarkers have been proposed to improve diagnosis by differentiating AD and psoriasis in patients with psoriasiform dermatitis, namely nitric oxide synthase 2 (NOS2) and CTACK/CCL27." (PMID 36012878, 2022). "Association to NOS2 has previously been reported to psoriasis; however no such association has been made to PTPN22." (PMID 25923216, 2015). "Although only applied three times on established psoriasis-like skin, we found a similar effect on the psoriatic inflammation and proliferation as in the NOS2 KO mice, supporting the hypothesis that a continuous application of an NO-releasing cream would alleviate psoriatic inflammation." (PMID 38926337, 2024). "In fact, using the imiquimod psoriasis mouse model, we found a profound impact on the psoriatic inflammation in both IMQ-treated NOS2 KO mice and wild-type mice treated with IMQ and the NO-releasing berdazimer gel." (PMID 38926337, 2024). "Additionally, markers like NOS2 and CCL27 (CTACK) have shown significant utility in distinguishing AD from psoriasis." (PMID 40141720, 2025). "Furthermore, α-humulene and torilin from Cnidi fructus were identified as targeting psoriasis-related proteins, including IL1B, TNF, NOS2, and NFKBIA." (PMID 39590306, 2024). "Our data thus suggest that the upregulated mRNA expression in psoriasis is not fully translated into NOS2 protein." (PMID 38926337, 2024). "Using the IMQ psoriasis mouse model in NOS2 KO mice, we found a reduced neutrophilic infiltrate and a lower expression of epidermal Ki67 and PCNA, suggesting that the NOS2 protein expression, which was present at low levels in response to IMQ in control mice, contributes to the psoriatic phenotype." (PMID 38926337, 2024). "Like in human psoriasis, we found that the NOS2 protein expression was not evidently upregulated in response to IMQ." (PMID 38926337, 2024). "Regarding the candidate targets, estrogen receptor (ESR1) showed the highest degree (113°), followed by PTGS2 (86°), NOS2 (81°), PPARG (60°), and GSK3B (56°), which demonstrated the potential therapeutic effect of each drug in LXJD formula for ameliorating psoriasis." (PMID 34168554, 2021). "Upregulation of the STAT1/NOS2 pathway has not been reported in HI before; however, it has been described in other inflammatory skin diseases, such as psoriasis and atopic dermatitis, sharing characteristics of skin barrier impairment and increased inflammation." (PMID 32544098, 2020).
melanoma (26 papers, 2005 to 2026). A malignant, usually aggressive tumor composed of atypical, neoplastic melanocytes. "In the context of melanoma, studies indicate that NOS2 promotes tumor proliferation and is associated with poor patient survival and increased resistance to cisplatin." (PMID 41535256, 2026). "Elevated NOS2 expression has been identified in precancerous lesions and numerous studies suggest a potential use of NOS2 as a predictive cancer biomarker with high NOS2 tumor expression being associated with poor patient survival in several types of cancer including melanoma, prostate, and breast." (PMID 22957045, 2012). "Three subtypes of NOSs have been demonstrated to be involved in melanoma progression by promoting melanoma cell proliferation, invasion, resistance to apoptosis and metastasis, with NOS2 correlating with poor patient survival." (PMID 41535256, 2026). "The nitric oxide synthase 2 (NOS2) gene, known to induce the metastatic ability of canine melanoma, was found to be upregulated." (PMID 41227463, 2025). "Significantly higher levels of Ifng, Nos2, Il12, Ccl5, Cx3cl1, and Cxcl9 — and, by contrast, significantly lower levels of Arg1 — were detected in the melanomas of Colec11–/– mice, compared with WT mice." (PMID 36883567, 2023). "Elevated NOS2 in human melanoma amplifies P13/AKT, HIF, and Ras pathways, TGF beta expression, and lower immune function." (PMID 38260202, 2023). "Ret mice with a more aggressive melanoma showed a high infiltration of NOS2 expressing γδ T cells and were enriched in pro-inflammatory cytokines IL-1β and IL-6." (PMID 34831116, 2021). "Recently, we detected NOS2 expressing γδ T cells within the primary tumor of melanoma patients, but also in the primary tumor and tumor draining LNs in mice transgenic for the Ret oncogene developing a spontaneous metastatic melanoma (model Ret)." (PMID 27812136, 2016). "We have recently shown that NOS2 improves the recruitment of γδ T cells within the tumor microenvironment in a murine model of spontaneous melanoma." (PMID 27812136, 2016). "Activation of NOS2 has also been demonstrated in lung, colon and prostate cancer and in melanoma and has been related to cervical lymph node metastasis and to greater metastatic potential." (PMID 24316703, 2014). "While therapeutic STING agonism coordinately enhanced expression of the Arg2, Isg15, Nos2, and Pdl1 (Cd274) immuno-suppressive/regulatory ISGs in both melanoma models, Cox2/Ptgs2 expression was selectively upregulated by ADU-S100 treatment only in the B16 model." (PMID 38312842, 2024). "Moreover, the presence of NOS2 reduced the killing capacity of γδ T cells against melanoma cell lines." (PMID 34831116, 2021). "In melanoma, increased NOS2 expression was correlated with worse prognosis and poor survival." (PMID 34502464, 2021). "Targeting of effector functions can be achieved via inhibition of phosphodiesterase, reducing expression of Arg1 and iNOS, similar to the HDAC inhibitor entinostat, which reduces expression of COX2, Arg1, and NOS2 in mouse models of melanoma and renal carcinoma." (PMID 31849950, 2019). "Similarly, elevated NOS2 tumor expression predicted poor survival in Stage III melanoma patients." (PMID 38892290, 2024). "Mice bearing either B16 (BRAFWTPTENWT) or BPR20 (BRAFV600EPTEN-/-) melanomas were treated with STING agonist ADU-S100 plus various inhibitors of ARG2, COX2, NOS2, PD-L1, or ISG15." (PMID 38312842, 2024). "According to our analysis, 66% of the isoforms presented differential expression on melanoma progression: NOS2, SOD1, NOX4, PRX3, PXDN and GPX1 are increased during melanoma progression, while CAT, GPX3, TXNIP, and PRX2 are decreased." (PMID 35326089, 2022). "We then analyzed the regulation of NOS2 gene expression by type I IFN in peripheral blood mononuclear cells (PBMC) from eight healthy volunteers (HV) and four melanoma (MEL) patients together with TILs from seven stage III/IV MEL patients." (PMID 31481761, 2019).
melanoma (continued). "Furthermore, our data analysis showed that 14% of the melanoma patients have genetic alteration on NOS1 gene, 8% on NOS2 and 18% on NOS3." (PMID 35326089, 2022). "In a melanoma model, snoRNA derived nuclear RNA3 (sdnRNA3) was found to be induced in DCs and may function to regulate iNOS expression via histone modification H3K27me3 at Nos2 gene promoter." (PMID 37006268, 2023). "In the B16 melanoma model, we noted improved antitumor efficacy only when ADU-S100 was combined with neutralizing/blocking antibodies against PD-L1 or ISG15, but not inhibitors of ARG2, COX2, or NOS2." (PMID 38312842, 2024). "However, tumor growth in two different models, B16 melanoma and MC38 colon carcinoma, showed significantly increased progression and resulted in decreased survival rates in animals lacking Nos2 in the T-cell compartment." (PMID 36574610, 2023). "It has been illustrated that the induction of melanoma metastasis declines in mice lacking CD73 dramatically since, among TILs belonging to these mice, the numbers of mannose receptor‐positive macrophages are decreased while IFN‐γ and NOS2 mRNA production is increased." (PMID 32902664, 2021).
colon carcinoma (22 papers, 2007 to 2025). "In the previous analysis, we found that NOS2 was significantly down-regulated in the high-risk group, and in the left-sided and right-sided colon cancer, patients with T3-4 and stage III-IV had relatively high risk score levels." (PMID 35265525, 2022). "At the same time, NOS2 was downregulated in colon tumor and associated with poor prognosis of COAD patients." (PMID 35655081, 2022). "We have previously reported that miR-21 expression is associated with NOS2 expression in colon cancer providing more confidence that this association is relevant." (PMID 22970173, 2012). "We hypothesized that the potential influence of the NOS2 gene polymorphism on cancer development may vary between right-sided and left-sided colon cancers, and rectal cancers." (PMID 38398251, 2024). "NOS2 is expressed in 50–60% of colon cancer patients, and those with high NOS2 expression have the prognosis." (PMID 40642105, 2025). "According to earlier research, IFNγ is critical for the stimulation of NOS2 in DLD1 (human colon cancer) cells." (PMID 37169743, 2023). "NOS2 has been demonstrated to possess anti-tumoricidal functions and to predict poor patient outcomes in several cancer types, including stomach and colon cancer, as it correlates with increased vascularization and metastasis." (PMID 37688629, 2023). "The infiltration of NOS2-positive macrophages cells correlates to a comparable beneficial prognostic effect in stage I-II colon cancers." (PMID 35962309, 2022). "Since the expression of ALOXE3 in colon cancer is closely related to tumor invasion and metastasis, we further analyzed the correlation between NOS2, ALOXE3 and clinical prognosis of patients." (PMID 35265525, 2022). "JAK2 has been shown to be activated in response to a wide variety of stimuli and AG-490 to block induced NOS2 expression in IL-1β/TNFα/IFNγ-stimulated human epithelial-like colon carcinoma DLD-1 cells and in IFNγ/LPS stimulated RAW cells." (PMID 18036230, 2007). "In the primary stages of colon cancer, low NOS2 expression is found." (PMID 40642105, 2025). "NO produced by NOS2 exacerbates colon cancer at inflammatory sites." (PMID 40642105, 2025). "In conclusion, NOS2 may have multiple roles in the induction and early progression of colon cancer as well as in the late stage." (PMID 35265525, 2022). "NOS2 expression is associated with colon cancer progression, but its role in tumor development is not clear." (PMID 35265525, 2022). "We found that NOS2 could simultaneously affect the prognosis of patients with left-sided and right-sided colon cancer." (PMID 35265525, 2022). "Studies in the early 2000s showed that NOS2 is present in 50%-60% of colon cancer patients." (PMID 35265525, 2022). "NOS2 and NOS3 promote colon cancer’s migration and invasive capacity by activating soluble guanylate cyclase." (PMID 40642105, 2025). "Correlation between NOS2, ALOXE3 expression levels and clinicopathological characteristics of patients with colon cancer." (PMID 35265525, 2022). "Several inflammation-associated genes such as cyclooxygenase-2 (COX-2), nitric oxide (NO), nitric oxide synthase 2 (NOS-2), and the interferon-inducible gene 1-8 U are increased in inflamed mucosa and remain elevated in colonic neoplasms." (PMID 36550412, 2022). "NOS2 has a major role in the activation of COX-2, which is an immediate—early response proinflammatory gene that is upregulated in nearly all colon cancers." (PMID 24392268, 2012). "In healthy individuals, NOS2 expression is absent in colon epithelial cells, and it is low-to-intermediate in patients with chronic colitis and is high in patients with colon cancer." (PMID 40642105, 2025).
colon carcinoma (continued). "Specifically, CDC25C, ANKRD22, SEZ6L2, SERPINA1, and NOS2 were overexpressed in colon cancer tissues compared with normal tissues." (PMID 41425595, 2025). "Nitric oxide (NO)-aspirin, a nitric oxide releasing prodrug of aspirin, inhibits the catalytic activity of nitric oxide synthase (NOS)-2, along with two COX-2, as well as down regulated expression of β-catenin and proliferating cell nuclear antigen (PCNA) in colon tumors induced by azoxymethane." (PMID 30096840, 2018). "On the other hand, we have not verified the cell experiments and mouse tumorigenesis experiments, and have not further explored the mechanism of NOS2, IFNG and ALOXE3 in the occurrence and development of colon cancer." (PMID 35265525, 2022).
Hypertension (22 papers, 2009 to 2025). The presence of chronic increased pressure in the systemic arterial system. "Numerous genes, including PTPN1 and NOS2, have been linked to the emergence of hypertension in leishmaniasis patients." (PMID 37571339, 2023). "Blood pressure and hypertension have been linked to NOS2 deficiency." (PMID 37571339, 2023). "Several PPAR target genes participate in hypertension with developmental origins, such as Sirt7, Nrf2, Nos2, Nos3 Ren, Sod2, and Sgk1." (PMID 39769369, 2024). "Estradiol, 17-beta-isomer of estradiol, has the shortest path from its target NOS2 to hypertension through NOS2, ATP2A2, and ‘calcium ion binding’ in muscle cells in myocardium." (PMID 28790372, 2017). "Back to the compound target network, luteolin and quercetin were found to influence NOS3 and NOS2 tested targets directly for hypertension, future studies should recognize the role of these compounds in CIF, and pharmacokinetic parameters should be calculated in both healthy and disease." (PMID 34055010, 2021). "It has been shown that administering the NOS2 inhibitor, 1400 W, prevented RUPP-induced hypertension in rats." (PMID 34681920, 2021). "The aim of the review is to study the role of SNVs of the NOS1, NOS2, and NOS3 genes in the comorbidity of arterial hypertension and tension-type headache." (PMID 33809023, 2021). "Compounds (for example, Angustidine) targeting proteins in sub-modules (such as NOS2 and NOS3) may effect on both AD and hypertension." (PMID 29997503, 2018).
endothelial dysfunction (21 papers, 2012 to 2025). In vascular diseases, endothelial dysfunction is a systemic pathological state of the endothelium (the inner lining of blood vessels) and can be broadly defined as an imbalance between vasodilating and vasoconstricting substances produced by (or acting on) the endothelium. "The set includes genes such as CLDN18, NOS2, SLC4A1, CA4, COL17A1, and SP7, many of which have been implicated in vascular inflammation, endothelial dysfunction, and extracellular matrix remodelling." (PMID 41226477, 2025). "A recent study on endothelial dysfunction in umbilical cord arteries and veins originating from neonates exposed to heavy maternal tobacco smoking detected an increase in the formation of ROS and upregulation of the NOS2-NO-producing pathway." (PMID 37510630, 2023). "It was hypothesized that this polymorphic site in the NOS2 gene can be involved in the development of endothelial dysfunction and essential AH through modulation of the NO level in inflammation." (PMID 33809023, 2021). "Therefore, SB modulation of the NOS2 might be beneficial for the endothelial dysfunction in hyperglycemia." (PMID 31687075, 2019). "In the third phase, NOS-2 and COX-2 expression are decreased, PGI2 synthase is nitrated/inactivated due to huge amounts of ROS and peroxynitrite from infiltrated leukocytes and endothelial dysfunction, at least in the larger vessels, is observed." (PMID 29057830, 2017). "Oxidative stress may lead to endothelial dysfunction, which could result in increased mean arterial pressure, and NO may play a role in this mechanism, but interactions with other vasoactive /biological substances cannot be overlooked, as the gene expressions of NOS3 and NOS2 have been reduced." (PMID 35100630, 2022).